PLK1 (polo like kinase 1)
Diseases named in the same sentence as PLK1 in open-access papers (continued):
Sharing a sentence is not in itself a finding about the gene and the disease.
tumor (continued). "Inhibition of PLK1 with the small molecule BI 2536 causes increased proteasomal degradation of PAX3-FOXO1 and tumor regression in a xenograft mouse model, an effect that could be reproduced in a different study using the PLK1 inhibitor Volasertib." (PMID 31970591, 2019). "Remarkably, in the last years, we started to gather strong evidence showing that Plk1 might also play as a tumor suppressor." (PMID 30862113, 2019). "Previous studies reported a correlation between Plk1 protein overexpression and lymphatic and distant metastases in several tumor types, suggesting that Plk1 might be involved in the metastatic process." (PMID 30859681, 2019). "PLK1 is highly expressed in tumour cells and is involved in almost all the processes of mitosis." (PMID 31275405, 2019). "Likewise, miR-100-5p, which modulates apoptosis and cell growth by targeting plk1, was reported to be down-regulated in HCC tumor and its low expression was associated with worse prognosis." (PMID 31320713, 2019). "A number of tumour models is sensitive to proteasome and PLK1 inhibitors." (PMID 30375513, 2018). "The correlations of PLK1 expression with the immune signature could be affected by other factors such as patient age, gender, tumor stage, and grade." (PMID 30631355, 2018). "In addition, 25% of Her2/Plk1 tumor cells became polyploid while this only occurred in 3% of Her2 tumor cells." (PMID 30069007, 2018). "A main mechanism by which PLK1 inhibits antitumor immunity lies in that the PLK1 upregulation activates the cell cycle which may decrease tumor immunogenicity." (PMID 30631355, 2018). "Moreover, intratumoral administration of A10-Plk1 AsiC in LNCaP-bearing athymic mice resulted in significant tumor regression when compared to the corresponding controls, such as PSMA-negative cells (PC-3) and A10mut-Plk1." (PMID 30340426, 2018). "To monitor the effects of Plk1 overexpression during tumor development in vivo, we used a mouse mammary gland tumor model in which an oncogenic Kras (KrasG12D) allele is induced by a tetracycline transactivator expressed under the control of the mammary gland tumor virus (MMTV) sequences." (PMID 30069007, 2018). "In vitro and in vivo experiments demonstrated the excellent performance of the CS-CD with a shell of siRNA in the following areas: entering cancer cells, efficient down-regulation of Plk1 gene (regulates mitosis and is often overexpressed in tumor cells), and potent tumor inhibition effects." (PMID 29914214, 2018). "Polo‐like kinase 1 protein (PLK1) was reported to highly express in various tumours." (PMID 30133120, 2018). "In addition, these Plk1-overexpressing tumor cells displayed a higher frequency of aneuploidy and polyploidy compared to the single oncogene tumors." (PMID 30069007, 2018). "PLK1 is overexpressed in several tumor types including NSCLC." (PMID 29983892, 2018). "Therefore, despite the therapeutic benefits of inhibiting Plk1 due to its essential role in tumor cell cycles, Plk1 overexpression has tumor-suppressive properties by perturbing mitotic progression and cytokinesis." (PMID 30069007, 2018). "Indeed, genes belonging to the ubiquitin-proteasome system can be found in all clusters and PLK1 expression is higher in cluster 2 tumours compared to the others." (PMID 30375513, 2018). "All together, these data indicate that, despite being generally considered as an oncogene, PLK1 may have tumor-suppressive activities." (PMID 30069007, 2018). "We found that a combination of PLK1 inhibitor and rhTRAIL significantly reduces tumor growth." (PMID 29983892, 2018). "Polo-like kinase 1 (PLK-1) inhibitors have shown promising results in tumor cells." (PMID 30304810, 2018).
tumor (continued). "Additional evidence for a tumor-suppressive role of Plk1 came from experiments showing that heterozygous knockout mice developed tumors at a 3-fold-higher frequency than wild-type mice, confirming a role of Plk1 in early development and tumor suppression." (PMID 29549256, 2018). "This means that when the expression level of CCNB1, CDC25C, CDK1 and PLK1 is reduced, the abilities in tumor cells proliferation could be inhibited at the same time." (PMID 29500418, 2018). "The overexpression of Plk1 was found in many tumor tissues and model tumor cells, e.g., A375 cells." (PMID 29201613, 2017). "Our findings are expected to stimulate further studies on whether PLK1 could be a potential therapeutic target for this tumor." (PMID 28887496, 2017). "Recently, a wealth of data has shed new light on the additional biochemical functions of PLK1 proteins and on the mechanisms through which they function in neoplastic transformation, tumor progression and dissemination, and the development of therapeutic resistance." (PMID 28953239, 2017). "However, emerging evidence suggests novel and previously unanticipated roles for PLK1 during tumor development." (PMID 28953239, 2017). "The tumor cells from mice treated with A10-liposome-PLK1 CRISPR/Cas9 chimeras, in contrast to those from mice treated with PBS, free CRISPR/Cas9, or A10-liposome-scrambled CRISPR/Cas9 chimeras, were vacuolated, extensively granulated, and showed evidence of necrosis." (PMID 28030843, 2017). "Collectively, this study suggests that PLK1 overexpression could play vital roles in the carcinogenesis and deterioration of GC via regulating tumor-related pathways." (PMID 29190933, 2017). "Interestingly, both PLK1-co-activated and ER-targeted genes were enriched in developmental function and act as tumor suppressor factors, suggesting a potential interaction of PLK1 with ERs." (PMID 28915707, 2017). "Next, we tested whether PLK1 inhibition in preneoplastic cells affects spindle formation in a similar way as was previously demonstrated for tumor cells." (PMID 29228663, 2017). "Furthermore, we observed significant differences between PLK1 high and low expression levels regarding tumor pathological stage." (PMID 29190933, 2017). "Furthermore, high expression of PLK1 protein was correlated with differentiated degree, clinical stage, tumor size, lymph node metastasis, and distant metastasis." (PMID 28724602, 2017). "There is increasing evidence that elevated PLK1 activity might serve as a tumor-promoting force by stimulating mitotic transcriptional programs to evade the DNA damage checkpoint." (PMID 28036269, 2017). "As a coactor of ERCC6L, PLK1 has been well known as a genetic marker of tumor cell proliferation." (PMID 28178669, 2017). "In addition, the serine/threonine-protein kinase PLK1, a trigger of G2/M progression, is highly expressed in tumor cells." (PMID 29161257, 2017). "In a clinical setting, inhibition of PLK1 might be useful for both HNSCC tumor treatment as well as prevention of tumors and local relapses." (PMID 29228663, 2017). "siRNA-mediated depletion of PLK-1 inhibits the tumor growth, both in vivo and in vitro." (PMID 28415805, 2017). "To address whether G6PD-mediated PPP pathway is important for Plk1-regulated tumor growth, we performed xenograft experiments using Hep3B and HeLa cells." (PMID 29138396, 2017). "Consistent with its role in mitosis, PLK1 is highly expressed in the late G2 and M phases of the cell cycle, and enhanced PLK1 activity is observed in cells with high mitotic rates, including tumor cells." (PMID 28953239, 2017). "Unintended toxic effects on primary cells, such as ASCs, could be partly responsible for the reported moderate anti-tumor activity in patients treated systematically with Plk1 inhibitors." (PMID 27713178, 2016). "ER maleate treated tumor xenografts showed reduced PLK1 and Syk expression." (PMID 26934445, 2016).
tumor (continued). "Our data indicated that preC-pol overexpression in the LFCD mutant could exert an effect mimicking that of anti-miR-100, resulting in PLK1 up-regulation to promote tumor growth." (PMID 26824500, 2016). "In addition, siRNA against PLK1 increased apoptosis in Huh-7 cell line in a caspase-independent manner and induced tumor regression in siPLK1-treated mice." (PMID 26799423, 2016). "Reduction of oral xenograft tumor volume with paralleling decrease in Syk and PLK1 expression, as well as chemosensitization of platinum drug in vivo, together with overexpression of Syk and PLK1 in clinical OSCCs provided evidence for development of ER maleate as a novel therapeutic agent for OSCC." (PMID 26934445, 2016). "We hypothesized that PLK1 inhibitor BI6727 could reduce the tumor-initiating cell population due to its ability to kill cisplatin-resistant cells." (PMID 27558154, 2016). "The Plk1 expression level is well known to be tightly correlated with the invasion of tumor cells." (PMID 27713178, 2016). "PLK1 may play an oncogenic role in tumor survival and growth, as inhibition of PLK1 by shRNA or small molecule inhibitors has been shown to decrease cell proliferation both in vitro and in vivo." (PMID 27538997, 2016). "Moreover, Plk1 is highly expressed in various entities of malignancy and is closely correlated with poor prognosis of tumor patients." (PMID 27713178, 2016). "Intratumoral injections of Plk1 inhibitor in ccRCC xenograft nude mice induced a tumor volume decrease indicating that a sustained inhibition of Plk1 function may inhibit ccRCC tumor growth in vivo." (PMID 26579493, 2015). "PLK1 overexpression, reported in several human tumor types, has been correlated with bad prognosis." (PMID 25826089, 2015). "Importantly, PLK1 is highly expressed in different tumor types including NSCLC, and is often correlated with aggressive disease and poor survival." (PMID 25557168, 2015). "Indeed, depletion of PLK1 gene expression results in inhibition of proliferation due to accumulation in the mitotic phase and apoptosis induction in tumor cell lines." (PMID 25826089, 2015). "PLK1 scores in the tumour periphery were significantly different to adjacent normal mucosa." (PMID 26047016, 2015). "Compared to normal mucosa away from the tumour, the peripheral PLK1 score was significantly higher." (PMID 26047016, 2015). "In the present work, we show that p21 impacts the efficacy of Plk1 inhibition in tumor cells." (PMID 25483104, 2015). "We investigated whether the relationship between drug-induced PLK1 downregulation and apoptotic cell death induction was a consistent event in tumor cell response to CPTs." (PMID 25826089, 2015). "Moreover, our data is consistent with previous reports showing that inhibition of PLK1 using either chemical inhibitors or RNAi induces mitotic arrest in tumor cells which leads to a reduction in cell proliferation and increased cell death." (PMID 25557168, 2015). "Additionally, GSK461364A showed not only in vitro inhibition of PLK-1 but also dose-dependent tumor growth inhibition in various established tumor xenografts." (PMID 26557691, 2015). "Moreover, the overexpression of Plk1 in various tumor tissues is closely correlated with the poor prognosis of patients, and has been thus regarded as one of the most promising targets for molecular anticancer therapy." (PMID 25483104, 2015). "Furthermore, long-term treatment with Plk1 inhibitors induced fiercely the senescent state of tumor cells with functional p21." (PMID 25483104, 2015). "Moreover, injection of clinically acceptable amounts of iNOP-7 PLK1 siRNA decreased lung tumor bioluminescence by 50% (indication of reduced tumor burden) when compared to mice treated with iNOP-7 control siRNA." (PMID 25557168, 2015). "Obviously, the presence of p21 protects tumor cells from severe damage upon Plk1 inhibition." (PMID 25483104, 2015).
tumor (continued). "We then examined whether PLK1 has an important role in controlling cell apoptosis, for it can decide the tumor status." (PMID 25019081, 2014). "Therefore, contrary to the positive relationship of PLK1 and some types of tumor malignance, less correlation of PLK1 and HCC malignancy was observed in the present study." (PMID 25019081, 2014). "The PLK1 gene expression was evaluated by extracting total RNA from the tumor tissues." (PMID 24159333, 2013). "Recently, multiple studies have reported that Plk1 is a potential therapeutic target for eliminating tumor-initiating cells in various tumor types, implying that inhibiting Plk1 could be useful for combating relapse and metastasis of tumors." (PMID 23948487, 2013). "Over the years, a great deal of effort has been focused on the design and synthesis of potent, linear peptide inhibitors targeting the polo-like kinase 1 (Plk1), which is critically involved in multiple mitotic processes and has been established as an adverse prognostic marker for tumor patients." (PMID 24223211, 2013). "In mice bearing MDA-MB-435 s.c. xenografts, the micelleplex carrying both Plk1 siRNA and paclitaxel was shown to simultaneous deliver the two agents at the designated ratio to the same tumor cells and synergistically suppress tumor growth, which was significantly more potent than Taxol®." (PMID 24300405, 2013). "In our previous study, we have shown that high PLK1 protein expression was significantly correlated with higher clinical stage, advanced tumor classification and lymph node metastasis of NSCLC patients and might be a poor prognostic molecular marker." (PMID 23151088, 2012). "Moreover, upregulated PLK1 expression is often observed in tumor cells and this has been shown to be correlated with poor prognosis due to enhanced mitotic activity." (PMID 23056340, 2012). "In addition, the impact of depleting PLK1 mRNA on tumor-initiating cells was evaluated using tumor sphere assays." (PMID 22390279, 2012). "Together, these results suggest that low miR-100 expression may be an independent poor prognostic factor and miR-100 can function as a tumor suppressor by targeting PLK1 in human EOCs." (PMID 22246341, 2012). "The high PLK1 in CD44high cells may help maintain TICs and the ongoing proliferation of the tumor-initiating population." (PMID 22309939, 2012). "Our findings indicate that low miR-100 may be a poor prognostic factor for NSCLC patients and functions as a tumor suppressor by posttranscriptionally regulating PLK1 expression." (PMID 23151088, 2012). "Notably, this applies to a compact module of cell cycle regulators, namely survivin, cyclin B1, Cdk1, Plk1, and Bub1, whose expression increased about 2-fold in tumor versus transgenic cells according to measured fold changes." (PMID 21464922, 2011). "This represents a novel form of regulation for Plk1 that may have implications for its expression in other tumour types." (PMID 21324136, 2011). "Inhibition of PLK-1 activity induces mitotic arrest and tumor cell apoptosis." (PMID 21884621, 2011). "Downregulation of cyclin A2 (Ccna2), Polo-like kinase 1 (Plk1) and the centromer protein A (Cenpa) which are typically upregulated in tumour cells to foster cell cycle and mitosis agree well with the observed cell cycle arrest and demonstrate the therapeutic effect of these experimental inhibitors." (PMID 21152443, 2010). "Thus, PLK1 is overexpressed in a wide range of human tumours, with high expression levels often correlating with poor prognosis." (PMID 20711360, 2010).
tumor (continued). "Moreover, correlated with the tumor phenotype, analysis of pre-malignant splenocytes displayed elevated aneuploidy in Plk1 heterozygous mice." (PMID 19161615, 2009). "PLK-1 is a critical component responsible for tumor progression." (PMID 19775446, 2009). "Cytoplasmic and some brown nuclear staining in tumor cells served as an index of PLK-1 expression." (PMID 19775446, 2009). "Plk1 is overexpressed in human tumours, an event that correlates with poor prognosis." (PMID 17662039, 2007). "In those cases in which notable PLK1 expression was present and in which infiltrative tumour margins could be seen, PLK1 expression was accentuated on the leading edge of tumour invasion." (PMID 14970859, 2004). "Furthermore, phosphorylation of PHGDH by PLK1’s highly expression in tumor which includes both the tumor cells and tumor microenvironment cells amplified the effects on lipid synthesis, which might cause the enhanced fat production in the whole body of mice." (PMID 40475404, 2025). "Furthermore, onvansertib effectively reduced tumor growth in the transgenic LKB1fl/flp53fl/fl mouse model of endometrioid EC, which was accompanied by a reduction in the protein expression of Ki-67 and Plk1 and an increase in the expression of Bcl-xL in tumor tissues." (PMID 40166466, 2025). "However, some scientists found that PLK1 overexpression could induce chromosomal instability and suppress tumor development." (PMID 40581078, 2025). "RTL-P (reverse transcription at low dNTPs-PCR) and actinomycin D assays confirmed that SNORD3B-2 directed 2′-O-methylation modification of PLK1 mRNA, and the modification could promote the stability of PLK1 mRNA which could mediate tumor growth and metastasis in EC." (PMID 39634126, 2025). "The identified circuits highlight the context-dependent nature of plk1, wherein it typically promotes genomic instability in a variety of malignancies, yet may exhibit tumor-suppressive properties contingent upon the tumor microenvironment and specific deregulatory events." (PMID 40430225, 2025). "Additionally, CRISPR/Cas9-mediated PLK1 knockout or RNA interference (RNAi) approaches could further suppress tumor growth and increase sensitivity to DNA-damaging agents, providing a potential avenue for combination therapies." (PMID 40496862, 2025). "Thus, tumor cells upregulate genes such as PLK1 to support their survival and propagation." (PMID 40347943, 2025). "Similarly, the serine/threonine protein kinase PLK1, usually promoting cell proliferation in the G2/M phase and prevalent in various tumours, showed decreased expression during differentiation, suggesting its role in cell cycle arrest and increased radiosensitivity in GBM." (PMID 40070092, 2025). "In addition, in vivo studies showed that DHIE reduced tumor burden, significantly reduced the infiltration level of tumor proliferation-related marker Ki-67, and inhibited the expression of PLK1 in the mouse model, which was further enhanced when combined with DOX." (PMID 40093330, 2025). "Identification of Core Targets: Five critical anti-GC targets (CDK1, CCNA2, TOP2A, CHEK1, and PLK1) were identified, with a focus on their roles in cell cycle regulation and chemotherapy resistance, providing mechanistic insights into Diosgenin’s anti-tumor effects." (PMID 40487391, 2025). "ECT2 is a biomarker that can be used for diagnosis and prognostic prediction in HCC, and its overexpression could promote lactic acid production through the ECT2/PLK1/PTEN pathway, enhance tumor-associated macrophage infiltration, and suppress immune cell function." (PMID 37957902, 2024). "We hypothesized that PLK1 inhibition could sensitize tumor cells to PARP inhibition." (PMID 39039067, 2024). "Among all selected prognostic biomarkers, ESR1, PGR, BRTC, YWHAQ and PLK1 were recognized as crucial features; for clinical features, whether the patient has gone through chemotherapy/hormone therapy and the size of the tumor play an important role in model predictions." (PMID 36698767, 2023).